ARID1A (AT-rich interaction domain 1A)
Diseases named in the same sentence as ARID1A in open-access papers (continued):
Sharing a sentence is not in itself a finding about the gene and the disease.
tumor (continued). "Such a mechanism could underlie ARID1B‐driven oncogenesis, wherein elevated ARID1B suppresses tumor‐suppressive ARID1A, thereby altering the ARID1A‐dependent transcriptome to promote tumorigenesis." (PMID 40671262, 2025). "Another study on the function of the ARID1A gene in ICC cells elucidated that individuals with ALDH1A1 positivity had a poorer prognosis, suggesting that ARID1A inhibition of ALDH1A1 expression could play a role in tumor suppression." (PMID 40008905, 2025). "Furthermore, our functional experiments showed that the ARID1A-defective cells had enhanced cell survival and colony-forming abilities, suggesting a tumor-suppressive role of ARID1A in SCLC." (PMID 41049615, 2025). "We first curated tumor-derived cell lines bearing intact expression of full-length ARID1A and ARID1B, those with loss of expression of ARID1A, and those characterized by dual-loss of ARID1A and ARID1B, isolated nuclear material and performed immunoblot analyses for mSWI/SNF family subunits." (PMID 41279405, 2025). "This relationship is significant because it suggests that ARID1A mutations may cooperate with other genetic mutations, such as PIK3CA or PTEN loss, to promote aggressive tumor behavior." (PMID 40072110, 2025). "Its pleiotropic effects in different settings, its mutation pattern and distribution across a wide variety of different tumor entities as well as apparently conflicting functional and clinical data support the concept that ARID1A functions as a context-dependent tumor suppressor." (PMID 39843653, 2025). "Additionally, re-expression of ARID1A reduces cell proliferation, confirming its role as a tumor suppressor and ability to inhibit PI3K/AKT pathway activation." (PMID 41514650, 2025). "Although identified as a tumor suppressor, ARID1A loss does not enhance cell proliferation in short-term cell culture, as several papers have reported." (PMID 40369167, 2025). "ARID1A resists ER- driven proliferative signaling and tumor growth in endometrial cancer." (PMID 41514650, 2025). "Due to the suggested antagonistic activities on various cellular pathways, ARID1A may act as a tumor suppressor or oncoprotein dependent on the cellular context." (PMID 40170512, 2025). "However, the overall mutational landscape—including tumor mutational burden (TMB) and recurrent alterations in key genes like ARID1A and PBRM1—was largely overlapping between groups." (PMID 39941902, 2025). "ARID1A mutations have been associated with high levels of tumor-infiltrating lymphocytes and PD-L1 expression in CCC, but it is still debated whether ARID1A mutations can serve as a biomarker for immune checkpoint inhibitor treatment." (PMID 40459063, 2025). "Interestingly, however, the same study found that low expression of ARID1A also brought more cytotoxic T cells and monocytic lineage immune cells to the tumor microenvironment." (PMID 40429787, 2025). "Notably, ARID1A mutations in OCCC were tightly linked to immunogenic features, including elevated PD-L1 and CD8+ T cell expression (p < 0.001) and high tumor mutational burden (TMB; p = 0.006)." (PMID 41020848, 2025). "Similarly, a clinical trial with PI3K inhibitor copanlisib in PIK3CA- and ARID1A-mutant cancers demonstrated a significant decrease in tumor growth." (PMID 41514650, 2025). "ARID1A was upregulated in 51 (46%) tumor samples and downregulated in 59 (54%) tumor samples." (PMID 39796161, 2025). "A second extension could include synthetic lethal interactions with PARP and ATR inhibitors beyond BRCA loss and HRD, such as ARID1A and ATM mutations, which would further help identify tumours most likely to respond to specific treatments." (PMID 39875558, 2025).
tumor (continued). "The impact of ARID1A depletion in the regulation of tumour microenvironment should be emphasised." (PMID 40621620, 2025). "The second hit on ARID1A might support tumor growth and progression in other ways, for example, by increasing the genetic instability by interfering with efficient DNA damage repair." (PMID 40170512, 2025). "The tumour purity of the ARID1A mutant group was greater than that of the wild-type group." (PMID 40463905, 2025). "We also found a high density of tumor-infiltrating CD3+ T cells in ARID1A-low CRC patients." (PMID 40750787, 2025). "As a core subunit of the SWI/SNF chromatin remodeling complex, ARID1A deficiency may impair chromatin accessibility and lead to transcriptional repression of PTEN and other tumor suppressors." (PMID 41215803, 2025). "Moreover, we also found that the level of ARID1A was negatively correlated with ssDNA and tumor PD-L1 level." (PMID 40750787, 2025). "Additionally, ARID1A mRNA expression was also lower in tumor tissue compared to normal tissue in CRC." (PMID 40750787, 2025). "Thus, our results provide biological insights into the function of ARID1A as a tumor suppressor in SCLC and present a therapeutic strategy to target SCLC with high ARID1A expression." (PMID 41049615, 2025). "After 3 weeks of treatment, JQ1 alone retarded tumor growth in the presence of ARID1A." (PMID 41049615, 2025). "However, treatment with JQ1 inhibited tumor growth and reduced tumor weight much more in ARID1A KD tumors than in control tumors." (PMID 41049615, 2025). "Dysfunction of ARID1A can lead to immune escape of tumor cells by upregulating PD-L1." (PMID 40406134, 2025). "Additionally, we observed that ARID1A mutant FL showed significantly lower FAS protein expression in the FL tumor cell population." (PMID 39843653, 2025). "JMSU‐1 cells showed a strong IFN response and repression of several proliferation‐associated GO terms in the absence of ARID1A, which suggests that these tumor cells have adapted to cope with these potentially repressive effects." (PMID 40170512, 2025). "Targeted cancer gene panel sequencing of the primary tumor specimens identified a few additional mutations, including one patient each with pathogenic germline mutations in APC and ARID1A, while the remaining mutations were variants of unknown significance." (PMID 39567523, 2024). "Moreover, ARID1A mutations or low expression can improve the tumor microenvironment (TME) and enhance the response of the tumor to immunotherapy." (PMID 39322625, 2024). "In both tumor and liquid biopsies, we identified an increased frequency of alterations in genes involved in genome integrity or chromatin remodeling, including ARID1A (15%), PBRM1 (9%), and BAP1 (14%), which were validated using an in-house-developed immunohistochemistry panel." (PMID 38191492, 2024). "In addition, ARID1A mutation can lead to impaired interferon (IFN) gene expression and reduce tumor response to immunotherapy." (PMID 38725626, 2024). "Likewise, AT-rich interactive domain 1 A (ARID1A) is a tumor suppressor, which is frequently inactivated in many cancers." (PMID 39334449, 2024). "Inactivation of the ARID1A tumor suppressor can also occur post-translationally." (PMID 38727317, 2024). "As the tumor-node-metastasis (TNM) stage advanced, the proportion of ARID1A loss increased." (PMID 38811536, 2024). "However, homozygous or heterozygous ARID1A deletion in preexisting tumours enhances invasion and metastasis." (PMID 39471843, 2024). "The next step was to validate the tumor-suppressive function of Arid1a in vitro." (PMID 39123453, 2024).
tumor (continued). "ARID1A assessment by IHC may represent a potential prognostic biomarker related to several clinicopathological features, including tumor differentiation, nodal metastases, and specific GC TGCA subtypes." (PMID 38893181, 2024). "The samples with clonal expression deficiency were similar to those with intact ARID1A expression, and the tumor infiltrating lymphocytes did not increase significantly." (PMID 38555560, 2024). "Importantly, the sensitivity of ARID1A-deficient tumor cells to SR-4835, a CDK12/CDK13 inhibitor, suggests a promising therapeutic approach for individuals with ARID1A-mutant tumors." (PMID 38835016, 2024). "The lack of ARID1A has been associated with a higher presence of CD8+ tumor-infiltrating lymphocytes (TILs) and intratumoral CD8+ immune cells in EAOC, suggesting the potential effectiveness of targeted immunotherapy in this specific context." (PMID 38384812, 2024). "Intriguingly, ARID1A exhibits dualistic roles in oncogenesis—it is necessary for the initial stages of HCC yet acts to thwart tumor progression and metastasis in advanced stages, highlighting the intricate, stage‐dependent functions of ARID1A in cancer and the need for nuanced treatment strategies." (PMID 38374872, 2024). "Studies using comprehensive analysis of cancer genome sequencing have identified loss-of-function mutations in either ARID1A and/or ARID1B in various cells, suggesting that they may encode products related to tumor development." (PMID 38365747, 2024). "Loss of ARID1A led to increased levels of H3K9 and H3K27 acetylation at the USP9X promoter, upregulating the expression of USP9X and PRKAA2, which mediated the adaptation of tumour cells to glucose starvation." (PMID 39471843, 2024). "Patients with ARID1A deficiency, compared to ARID1A-proficient patients, exhibited increased infiltration levels of CD8 + P value < 0.0001), CD163 + P value < 0.001), and FOXP3 + P value < 0.001).cells within the tumor tissue." (PMID 38555560, 2024). "Moreover, the bias of ARID1A and SMARCA4 in different tumors and their pro- or anti-cancer effects in different tumors and different processes of tumor development have led to the incomplete study of ARID1A and SMARCA4 at present." (PMID 39697230, 2024). "This indicates that ARID1A loss can impact immune response to tumor cells via other mechanisms, and it is not restricted only to DSB repair deficiency and activation of cGAS/STING pathway." (PMID 38587186, 2024). "Among the nominally significantly mutated genes, ARID1A was most frequently mutated, with four nonsilent small mutations and one deletion (five tumours, 14%)." (PMID 38877653, 2024). "In this paper, we will focus on the role of the two most frequently mutated subunits of the SWI/SNF complex, ARID1A and SMARCA4, in tumors and their molecular mechanisms, as well as the anti-tumor therapeutic strategies that have been identified for the corresponding mutations." (PMID 39697230, 2024). "Previous research has indicated that ARID1A gene mutations in OCCC may be associated with the abnormal activation of the PI3K-AKT pathway, a key player in altering tumor growth, proliferation, and metastasis." (PMID 38725626, 2024). "In addition to its roles in tumorigenesis and gene expression, the role of ARID1A in regulation of tumor immune response has been proposed." (PMID 38555560, 2024). "As MNAC is an HPV-independent neoplasm, it follows a distinct pathophysiology and has been linked to several genetic mutations, including KRAS/NRAS, ARID1A, ARID1B, SMARCA4, and CTNNB1 mutations, along with chromosomal alterations such as gains of 1q, chromosomes 10 and 12, and loss of 1p." (PMID 39797200, 2024).
tumor (continued). "ARID1A was associated with carcinogenesis and metastasis in already established HCC tumours." (PMID 38536546, 2024). "For the pattern of complete expression deficiency (cdARID1A), ARID1A expression was absent in all tumor cells." (PMID 38555560, 2024). "In conclusion, we confirmed the tumour-suppressive effect of ARID1A in HCC." (PMID 38166741, 2024). "While this has yet to result in a new therapy for ARID1A-mutated tumours, the identification of a drug(s) that targets and abolishes ARID1B function in ARID1A-mutated tumours could represent a new therapeutic strategy for OCCC." (PMID 39272926, 2024). "In turn, the addition of PARP inhibitors to ARID1A-loss tumor cells and the addition of PARP inhibitors to the treatment of ARID1A-loss tumor cells could improve the responsiveness of cells to ATR inhibitors." (PMID 38347608, 2024). "PDX models developed represented similar genomic (e.g., ARID1A, PIK3CA, KRAS etc.)and protein (PAX8, ARID1A, napsin A, racemase) profiles to the native patient tumor from which they were derived supporting use of these models as surrogates of the patient tumor." (PMID 37841875, 2023). "The increased frequency of ARID1A 1038_1040del in tumor samples may arise from the increased instability of tumor genomes." (PMID 37414794, 2023). "Conversely, ARID1A deficiency leads to compromised NMR, which may provide one explanation of the tumor-suppressive role of ARID1A." (PMID 36980292, 2023). "The application of our ELISA on various tumor and control tissues will allow us to explore whether quantitative ARID1A measurements in tumor samples are of predictive value." (PMID 37627124, 2023). "The lack of ARID1A in tumors is associated with an increased tumor mutational burden and genomic instability, which is currently pharmacologically exploited according to synthetic lethality principles." (PMID 36890819, 2023). "Similarly, we explored human proteomics databases incuding the Clinical Proteomic Tumor Analysis Consortium (CPTAC) to correlate the expression between ARID1A and DUSP4, as well as MAPK molecules." (PMID 38071325, 2023). "We found the genetic alterations in PBRM1 and ARID1A to be present in 15–16% of tumor cells." (PMID 37400502, 2023). "Since the ARID1A-dependent transcriptome is likely to differ in different cellular contexts, the details of ARID1A-dependent tumor suppression or activation may be cell type specific." (PMID 37743426, 2023). "Interestingly, elevated ARID1A levels promote tumor initiation by increasing oxidative stress through Cytochrome P450 pathways." (PMID 37093326, 2023). "On the other hand, our results show that there is an increase in deviation from ‘same lysates’ to ‘different lysates’ (Columns 4 and 5), which might be due to a different ARID1A expression pattern in different tumor regions and is uninfluenceable." (PMID 37627124, 2023). "ARID1A has emerged as a tumor suppressor in a broad array of human malignancies." (PMID 36980292, 2023). "As the ARID1A and ARID1B proteins are mutually exclusive in the SWI/SNF complex, it could be proposed that the survival of tumor cells with ARID1A mutations may depend on the presence of ARID1B in the residual SWI/SNF complex." (PMID 37175555, 2023). "ARID1A deficiency was defined as the absence of tumor expression of its gene product (BAF250a) by IHC staining." (PMID 37711591, 2023).
tumor (continued). "BAF250a, the protein encoded by ARID1A, is one of the accessory subunits of the SWI–SNF complex chromatin remodelling complex which modulates the repression/de-repression of several promoters, and it acts as a tumour suppressor by nature." (PMID 36768291, 2023). "Mutations in KDM6A and ARID1A have been reported as the most frequently altered chromatin modifying genes in human UC regardless of tumor stage or grade, suggesting that they are early events." (PMID 37079639, 2023). "In fact, ARID1A relies on these mutations for tumor genesis, and mouse models have shown that ARID1A mutations alone, without PTEN, cannot drive cancer formation alone." (PMID 37465112, 2023). "Our results not only confirm known associations, such as mismatch repair and POLE gene mutations with high TMB, but also identify significant associations between mutations in the SWI/SNF chromatin remodelling genes ARID1A and SMARCA4 and high TMB in multiple tumour types." (PMID 37821580, 2023). "Additionally, treatment with the EZH2 inhibitor GSK126 resulted in the regression of ARID1A mutant tumours." (PMID 38041544, 2023). "However, studies using mice models suggest that the role of ARID1A in cancer is complex, and often context dependent, and it has both tumor-suppressive and oncogenic roles." (PMID 37093326, 2023). "These types may lead to disruption of protein functional domains or mediate mRNA degradation, thus disrupting ARID1A gene function and leading to tumor cell progression and patient recurrence." (PMID 37981695, 2023). "IGROV-1 is derived from a mixed histology tumor and contains mutant ARID1A and PIK3CA and could be considered a clear cell-like line." (PMID 37621654, 2023). "Hardly any literature is available on ARID1A levels in tumor samples." (PMID 37627124, 2023). "Our data, along with previous studies, demonstrate that ARID1A and 1B may have a role as tumor suppressors in OS progression, and may represent useful prognostic markers and potential therapeutic targets." (PMID 37373240, 2023). "Mutations of the ARID1A gene are associated with altered subunits in the SWitch/Sucrose Nonfermentable Complex (SWI/SNF), a protein involved in chromatin remodeling, and largely acts as a tumor suppressor." (PMID 37465112, 2023). "In this model, ARID1A haploinsufficiency is enough to drive tumor progression." (PMID 36890819, 2023). "Furthermore, the knockdown of ARID1A is enough for the malignant transformation of immortalized endometrial cells, suggestive of its role as a tumor suppressor." (PMID 37093326, 2023). "The high prevalence of ARID1A mutations in MSI cancers suggests that it has the potential to be a biomarker predicting sensitivity to immune checkpoint inhibition, along with tumour mutational burden, and TIL and PD-L1 expression, but this will need validation in large clinical trials." (PMID 38275587, 2023). "Collectively, we believe that ARID1A can suppress tumour metastasis in TNBC." (PMID 37173914, 2023). "Furthermore, additional research conducted by Li and colleagues on three GI cancer genomics datasets uncovered that ARID1A‐mutated GI cancers with elevated immune activity were associated with higher TMB and lower levels of tumour aneuploidy." (PMID 38041544, 2023). "In vivo targeting of ERK in ARID1A-deleted tumors slows tumor progression." (PMID 38071325, 2023). "ARID1A acts as a tumor suppressor gene with an epigenetic role in cancer development." (PMID 37711591, 2023).